TFRC (transferrin receptor)
Diseases named in the same sentence as TFRC in open-access papers (continued):
Sharing a sentence is not in itself a finding about the gene and the disease.
cardiomyopathy (10 papers, 2020 to 2025). A disease of the heart muscle or myocardium proper. "TFRC is linked with cardiomyopathy and was identified in our study as closely interacting with ACE2 in infected cardiomyocytes and is strongly connected with SARS interactome." (PMID 33233425, 2020). "In the analysis of iron metabolites and cardiomyopathy, there were 2 SNPs in SI, 69 SNPs in SF, 3 SNPs in STF, 2 SNPs in TFRC, and 24 SNPs in TSP; and SF was a risk factor for cardiomyopathy (OR = 1.750, 95%CI: 1.152~2.657, P = 0.009)." (PMID 41323136, 2025). "For example, mice lacking the cardiac transferrin receptor, Tfr1, in the heart experience severe cardiomyopathy and cardiac iron deficiency." (PMID 39568773, 2024). "It has reported that malnutrition-induced ID in growing rats leads to cardiomyopathy, and a recent study also showed that mice with transferrin receptor knockout in the heart may suffer from lethal cardiomyopathy involving impaired mitochondrial biogenesis." (PMID 31914941, 2020). "However, inactivation of TFRC leaded to lethal cardiomyopathy in mice." (PMID 37647427, 2023). "While there was no significant impact of SI, STF, TFRC, and TSP on the incidence risk of cardiomyopathy." (PMID 41323136, 2025). "The administration of nicotinamide riboside in a mice model of cardiomyopathy, lacking transferrin receptor protein 1 (TfR1) in the heart, has shown to prevent cardiomegaly, mitochondrial respiration, poor cardiac function, and impaired mitophagy." (PMID 34552808, 2021).
chronic kidney disease (10 papers, 2009 to 2025). Impairment of the renal function secondary to chronic kidney damage persisting for three or more months. "An altered expression of TFRC has been detected on mesangial cells in IgA nephropathy, and recently the TFRC gene was reported to be downregulated in tubules of samples derived from patients affected by chronic kidney diseases." (PMID 36769128, 2023).
hereditary hemochromatosis (10 papers, 2015 to 2025). An inherited metabolic disorder characterized by iron accumulation in the tissues. "We next examined if the expression levels of other genes associated with iron regulation, such as haemochromatosis (HFEs), bone morphogenetic protein receptors (BMPRs), transferrin receptor (TFRs) and hepcidin (HAMP), varied between human liver and HCC cell lines." (PMID 30135444, 2018). "Sensing of acute changes in serum iron concentration and transferrin saturation also converges on the BMP–SMAD pathway, involving transferrin receptor 1 (TfR1/CD71), transferrin receptor 2 (TfR2), the haemochromatosis protein HFE and BMP receptors (although not requiring BMP6 induction)." (PMID 30995720, 2019).
ischemia (10 papers, 2012 to 2024). A hypoperfusion of the BLOOD through an organ or tissue caused by a PATHOLOGIC CONSTRICTION or obstruction of its BLOOD VESSELS, or an absence of BLOOD CIRCULATION. "Intriguingly, the dynamin inhibitor dynasore, which has been shown to block transferrin receptor endocytosis, can protect from ischemia/reperfusion injury as well as neuronal cell death following spinal cord injury." (PMID 33050207, 2020). "The authors conjugated BDNF to the transferrin receptor antibody OX26 and demonstrated restoration of CA1 region in hippocampus after ischemia in rats after i.v. delivery of PEG-BDNF-OX26." (PMID 34149364, 2021). "First, elevated ROS levels during ischemia increase AR activity, leading to an increase in the cytoplasmic NADH / NAD + ratio, which further induces the expression of HIF-1α and the transcription of the transferrin receptor (TfR) gene, triggering ATP depletion and tissue damage." (PMID 37938421, 2023).
myocardial infarction (10 papers, 2013 to 2024). Gross necrosis of the myocardium, as a result of interruption of the blood supply to the area, as in coronary thrombosis. "Some of the studies carried out on Western populations have shown a relationship between body iron status as determined by the ratio of concentrations of serum soluble transferrin receptor (sTfR) to ferritin and the risk of acute myocardial infarction (AMI)." (PMID 23840800, 2013). "Although only a few studies have been focused on the relationship between myocardial infarction and TFRC expression, preclinical studies using TFRC knock-out mice have demonstrated that these animals had a loss of cardiac function, cardiomegaly, and mitochondrial anomalies." (PMID 35625854, 2022).
osteosarcoma (10 papers, 2019 to 2025). A usually aggressive malignant bone-forming mesenchymal neoplasm, predominantly affecting adolescents and young adults. "TFRC was highly expressed in osteosarcoma, and its high level of expression was associated with poor overall survival in osteosarcoma patients." (PMID 40510157, 2025). "The transfection of RRM2-overexpressing plasmids partially reversed the decrease in the proliferation, migration, and invasion ability of osteosarcoma cells caused by TFRC knockdown." (PMID 40510157, 2025). "In this study, we analyzed several public databases and reported that TFRC is overexpressed in osteosarcoma and that this overexpression is associated with poor overall survival in osteosarcoma patients." (PMID 40510157, 2025). "TFRC is upregulated in various types of cancer; although little is known about the role of TFRC in sarcoma, a recent study showed that it is associated with poor prognosis of osteosarcoma." (PMID 37444594, 2023). "The results revealed that in the GSE42352 dataset, the expression of TFRC in osteosarcoma cell lines (n=19) was significantly greater than that in mesenchymal stem cells (n=12) (P<0.001)." (PMID 40510157, 2025). "Through various experiments, we found that TFRC is generally highly expressed in osteosarcoma cells and affects the proliferation, migration and invasion of osteosarcoma cells by regulating the total intracellular iron level and RRM2 expression." (PMID 40510157, 2025). "We conducted experiments on the expression of TFRC in osteosarcoma, its influences on proliferation, migration, and invasion, and its mechanisms in vitro and in vivo to provide new ideas for the treatment of osteosarcoma." (PMID 40510157, 2025). "Our subsequent experiments confirmed that TFRC is overexpressed at the mRNA and protein levels in four osteosarcoma cell lines: MNNG/HOS, U2OS, MG-63, and 143B." (PMID 40510157, 2025). "Compared with that in control tissues, the expression of TFRC in osteosarcoma tissues was significantly greater, and the IHC staining score significantly differed (P<0.0001)." (PMID 40510157, 2025). "The results revealed significantly greater expression of TFRC mRNA and protein in osteosarcoma cell lines than in the human osteoblast cell line hFOB1.19." (PMID 40510157, 2025). "In the integrated datasets of TARGET-OS (n=88) and GTEx (n=396), TFRC was also significantly overexpressed in osteosarcoma tissues compared with normal skeletal muscle tissues (P<0.0001)." (PMID 40510157, 2025). "In previous experiments, we reported that TFRC was abnormally overexpressed in human osteosarcoma cells." (PMID 40510157, 2025). "Compared with 12 samples of osteoblastoma tissues, 30 samples of clinical osteosarcoma tissues also presented high expression level of TFRC as determined by immunohistochemical staining." (PMID 40510157, 2025). "The purpose of this study was to explore the role and mechanism of TFRC in the proliferation, invasion, and migration of osteosarcoma cells." (PMID 40510157, 2025). "Reviews of CD71 in cancer summarize evidence that TFRC elevation is associated with increased migration and invasion across tumor types, while TFRC knockdown reduces migration/invasion in osteosarcoma cells, supporting a pro-motility role." (PMID 41375568, 2025). "Therefore, TFRC is a very promising target for osteosarcoma therapy." (PMID 40510157, 2025). "Here, we investigated the potential of transferrin receptor-1 (TfR1) and vascular endothelial growth factor (VEGF) as prognostic markers of osteosarcoma." (PMID 31484533, 2019). "In addition, we used IHC staining to assess the protein expression of TFRC and RRM2 in human osteosarcoma tissues (n=30) and osteoblastoma tissues (n=12) as controls." (PMID 40510157, 2025).
asthma (9 papers, 2015 to 2024). "TFRC protein is also involved in the regulation of proliferation, as well as in the development of diseases such as cancer, atherosclerosis, pulmonary vascular remodeling, asthma, and lung fibrosis." (PMID 39273443, 2024). "For example, we provide supporting evidence for a role of IL4R in asthma, IL2RA in thyroid dysfunction, and IL12B in psoriasis, as well as many cellular phenotypes, such as Transferrin receptor protein 1 (encoded by TFRC) in mean corpuscular hemoglobin." (PMID 32628676, 2020). "Relationships between measures of iron status (serum ferritin, serum soluble transferrin receptor (sTfR), and sTfR/log10ferritin (sTfR-F Index)) and asthma, lung function, and pulmonary inflammation were examined in women 20-49 years in the National Health and Nutrition Examination Survey." (PMID 25689633, 2015). "Between moderate and mild asthma, KEGG analysis showed that the “HIF-1 signaling pathway” was the most significant signaling pathway, with TFRC, NOS2 and ERBB2enrichment." (PMID 38351296, 2024).
atherosclerosis (9 papers, 2013 to 2024). A disease characterized by the build-up of fatty material and calcium deposition in the arterial wall resulting in partial or complete occlusion of the arterial lumen. "In particular, the upregulation of ferritin heavy chain (FT-H) and transferrin receptor (TfR1) in the aorta may be the mechanism by which iron deposition promotes the progression of atherosclerosis." (PMID 37504565, 2023).
hemoglobinopathies (9 papers, 2006 to 2023). "An increased concentration of serum soluble transferrin receptor (sTfR) is associated with ID but also with increased erythropoiesis from congenital hemoglobinopathies, other causes of hemolysis, or ineffective erythropoiesis." (PMID 32053933, 2020). "Blood samples were collected before and after intervention for haemoglobin, serum ferritin (SF), serum transferrin receptor (TfR), C-reactive protein (CRP), and haemoglobinopathies analysis." (PMID 17147795, 2006).
iron metabolism disorders (9 papers, 2015 to 2023). "However, the expression of TF and TFRC was decreased at 24 h.p.i., and it may affect iron transport and eventually lead to iron disorder in cells." (PMID 35715835, 2022).
ischemic stroke (9 papers, 2015 to 2026). A stroke disorder caused by obstruction of blood flow to the brain, due to thrombotic (local blood clot formation) or embolic (due to a blood clot or other material traveling from another site) event. "Furthermore, in a mouse model of ischemic stroke, it was observed that free radicals and an excess of iron resulted in the prolonged upregulation of transferrin receptor 1 (TFR1), which subsequently led to an elevation in peripheral iron absorption, oxidative stress, and the demise of neurons." (PMID 37622048, 2023). "In this study, HAIYPRH (T7), a peptide that targeted to transferrin receptor (TfR) can mediate the transport of nanocarriers across the BBB, was conjugated to liposomes for ischemic stroke targeting treatment of a novel neuroprotectant (ZL006)." (PMID 26219474, 2015).
myeloma (9 papers, 2014 to 2025). "From the NOTATER output, it can be seen that TFRC is clearly expressed not only in myeloma cells, but also in the majority of healthy tissues, with the exception of NK-cells and monocytes." (PMID 38688994, 2024). "High-resolution fluorescence imaging and flow cytometry analyses showed that the nanoplatelets loaded with EPI and Cy5 targeted human myeloma cells (RPMI8226 cells) that over-expressed the transferrin receptor." (PMID 36836127, 2023). "The cytotoxic effect of HXR9 in myeloma cells was found to be enhanced if it was combined with this protein, suggesting that both HOX proteins and the transferrin receptor might be valid drug targets for multiple myeloma." (PMID 25525461, 2014). "Orthogonal delivery was achieved by coating TiO2 with apo-transferrin (Tf) and radiolabeling daratumumab to target transferrin receptors (CD71) and CD38, respectively, which are overexpressed on rapidly proliferating myeloma cells." (PMID 41041064, 2025). "Specifically, using a technique exploiting an anti-CD38 nanobody-based photoaffinity labeling, they discovered that cell surface CD38 interacts with the transferrin receptor CD71 and that the CD38-CD71 complex is present naturally in the myeloma cell line LP-1." (PMID 36078044, 2022). "However, there are also 26 proteins that are co-expressed with TFRC across those healthy tissues, but not in myeloma." (PMID 38688994, 2024).
pulmonary fibrosis (9 papers, 2019 to 2025). Chronic progressive interstitial lung disorder characterized by the replacement of the lung tissue by connective tissue, leading to progressive dyspnea, respiratory failure, or right heart failure. "And ferroptosis inhibitors combined with iron chelators and specific TFRC knockout have been shown to alleviate pulmonary fibrosis in mice." (PMID 40001138, 2025). "Besides, in mice with idiopathic pulmonary fibrosis, overexpression of TFRC leads to elevated intracellular Fe2+, which promotes fibroblast to myofibroblast transformation." (PMID 39251905, 2024). "Additionally, transferrin receptor, CD71, is downregulated in smokers, permitting inappropriate pulmonary bacterial growth and pulmonary fibrosis." (PMID 37822933, 2023). "For instance, in one study on pulmonary fibrosis, TGF-β1 was found to promote the transcription of TFRC in lung fibroblasts, leading to iron overload." (PMID 40001138, 2025).
breast tumor (8 papers, 2007 to 2024). "By showing overexpression of transferrin receptor in metastatic and pre-treated breast tumors from a large population, our study expands on the potential indications of transferrin conjugates for drug delivery or imaging." (PMID 38117806, 2023). "The expression of six HKs (TFRC, GUSB, GAPDH, ACTB, HPRT1 and RPLP0) was investigated using geNorm and NormFinder softwares in forty breast tumor, four normal and eight adjacent tissues." (PMID 21702980, 2011).
celiac disease (8 papers, 2019 to 2025). An autoimmune genetic disorder with an unknown pattern of inheritance that primarily affects the digestive tract. "In both IgAN and celiac disease, the transferrin receptor (TFR) is associated with transglutaminase 2 (TG2), both of which are present in enterocytes and mesangial cells." (PMID 38720942, 2024). "α1KICD89Tg mice also show an increased expression of transferrin receptor 1 (CD71), which is the major IgA1 receptor on the mesangial cell surface in IgAN patients and on the intestinal cell surface in celiac disease patients." (PMID 39519036, 2024). "One potential source can obviously be entrance of antibodies to the circulation through leaky epithelial surfaces, but active re-transportation mechanisms across the epithelium is suggested to exist for secretory antibodies via the CD71/transferrin receptor in some diseases like celiac disease." (PMID 41050553, 2025). "First of all, celiac disease and IgAN share molecular mechanisms that involve IgA1, transglutaminase 2 (TG2), and overexpression of Transferrin Receptor (TfR1, or CD71), a non-classical IgA receptor." (PMID 36467425, 2022).
endometrial cancer (8 papers, 2020 to 2025). Primary or metastatic malignant neoplasm involving the endometrium (mucous membrane that lines the endometrial cavity). "It was reported that circRAPGEF5 interacts with and inhibits the splicing regulator RNA-binding protein fox-1 homolog 2 (RBFOX2) to confer ferroptosis resistance by modulating the alternative splicing of TFRC in endometrial cancer cells." (PMID 37686142, 2023). "For example, circRAPGEF5 medicated ferroptosis by modulating alternative splicing of TFRC in endometrial cancer, and circRAPGEF5/RBFOX2 axis might be a cancer therapy target." (PMID 39170701, 2024). "Moreover, circRAPGEF5 was reported to change the splicing of TFRC by binding to and inhibiting RBFOX2 and then inhibiting iron uptake to repress the ferroptosis of endometrial cancer cells." (PMID 37686142, 2023).
head and neck cancer (8 papers, 1990 to 2024). A primary or metastatic malignant neoplasm affecting the head and neck. "Of the 11 EV-associated proteins that may be useful markers of nodal OTSCC, transferrin receptor protein 1 and integrin beta-1 have been identified by previous EV head and neck cancer studies." (PMID 34571828, 2021). "Data analysis and ranking of the top 5 HKGs using geNorm and Normfinder identified UBC, TBP, IPO8, TFRC, GAPDH in head and neck cancer; TBP, IPO8, GUSB, UBC in lung and TBP, IPO8, TFRC, GUSB, HMBS in pancreas to be stable." (PMID 28262749, 2017).
Hypertension (8 papers, 2012 to 2025). The presence of chronic increased pressure in the systemic arterial system. "However, as an indicator of iron metabolism, little is known about the associations of soluble transferrin receptor (sTfR) with hypertension." (PMID 36407469, 2022).
IgA nephropathy (7 papers, 2017 to 2026). "Mesangial CD71 (transferrin receptor) is overexpressed in patients with IgA nephropathy, colocalizing with Gd-IgA1 deposits." (PMID 32085673, 2020). "Several studies have demonstrated the presence of a molecule, CD71, a transferrin receptor, that binds polymeric IgA1 and is overexpressed on mesangial cells in patients with IgA nephropathy." (PMID 32824988, 2020). "In IgA nephropathy (IgA-N), these immune complexes are trapped in the glomerular mesangium by the mesangial transferrin receptor, which serves as an IgA1-sCD89 receptor." (PMID 29190714, 2017).
liver fibrosis (7 papers, 2022 to 2025). "This was associated with an inhibition of TFRC, indicating that miR-222 targets TRFC-induced ferroptosis which is a process that attenuates liver fibrosis." (PMID 39599900, 2024). "The implication of the miR-222 and the transferrin receptor (TFRC) in liver fibrosis was investigated in exosomes rich in miR-222 derived from HBV-infected hepatocytes." (PMID 39599900, 2024). "Previous studies have shown that exosomal miR-222 derived from HBV-infected hepatocytes aggravates liver fibrosis by inhibiting TFRC-induced ferroptosis." (PMID 39532842, 2024). "Exosomal miR-222 derived from hepatocytes with HBV infection accelerates liver fibrosis by repressing transferrin receptor (TFRC)-mediated ferroptosis." (PMID 37041599, 2023). "They first elucidated that ISL relieved liver fibrosis by inducing HSCs ferroptosis through repressing GPX4 expression and increasing the expression of transferrin receptor (TFR) and divalent metal transporter 1 (DMT1), thus producing a large number of ROS." (PMID 39512816, 2024).
malnutrition (7 papers, 2019 to 2024). Inadequate nutrition resulting from poor diet, malabsorption, or abnormal nutrient distribution. "More specific laboratory exams, such as retinol binding protein or transferrin receptor dosage, can be used in severely malnourished children to assess malnutrition over time, but they are hardly available in all centers." (PMID 35884438, 2022).
microcytic anemia (7 papers, 2014 to 2022). Anemia in which the red blood cell volume is decreased. "Irp2 depletion causes the deficiency of cellular functional iron by decreasing transferrin receptor and increasing ferritin expression, which compromise the heme biosynthesis and finally trigger microcytic anemia in mice and in humans." (PMID 34675764, 2021).
rheumatoid arthritis (7 papers, 2020 to 2025). A chronic, systemic autoimmune disorder characterized by inflammation in the synovial membranes and articular surfaces. "Whether TFRC regulates the function of osteoclasts through certain mechanisms, affecting bone metabolism balance and leading to the development of osteoporosis, rheumatoid arthritis, Paget’s disease of bone, etc., is also a topic worthy of further in-depth research." (PMID 40510157, 2025).